SLC26A2 (solute carrier family 26 member 2)
Description:
Sulfate transporter which mediates sulfate uptake into chondrocytes in order to maintain adequate sulfation of proteoglycans which is needed for cartilage development. Mediates electroneutral anion exchange of sulfate ions for oxalate ions and of sulfate and oxalate ions for chloride ions. Mediates exchange of sulfate and oxalate ions for hydroxyl ions and of chloride ions for bromide, iodide and nitrate ions (By similarity). The coupling of sulfate transport to both hydroxyl and chloride ions likely serves to ensure transport at both acidic pH when most sulfate uptake is mediated by sulfate-hydroxide exchange and alkaline pH when most sulfate uptake is mediated by sulfate-chloride exchange (By similarity). Essential for chondrocyte proliferation, differentiation and cell size expansion (By similarity).
Synonyms: DTD; DTDST; D5S1708; EDM4; MST153; MSTP157
Tractability: Antibody: UniProt places it where antibodies can reach, with high confidence; its Gene Ontology location is reachable by antibodies, with high confidence; UniProt predicts a signal peptide or a membrane-spanning region. PROTAC: ubiquitination databases record sites on it.
Gene: Protein-coding gene on chromosome 5 (149,960,758 to 149,993,455, forward strand). Ensembl gene ENSG00000155850.
Subcellular location: Cell membrane; Apical cell membrane
Subcellular location (Human Protein Atlas): Vesicles
Pathways (Reactome):
Disease: Defective SLC26A2 causes chondrodysplasias
Metabolism: Transport and metabolism of PAPS
Transport of small molecules: Inorganic anion exchange by SLC26 transporters
Gene Ontology:
Molecular function: oxalate transmembrane transporter activity; solute:inorganic anion antiporter activity; sulfate transmembrane transporter activity; chloride:bicarbonate antiporter activity; secondary active sulfate transmembrane transporter activity
Biological process: oxalate transport; sulfate transmembrane transport; chloride transmembrane transport; chondrocyte differentiation; chondrocyte proliferation; transmembrane transport
Cellular component: extracellular exosome; plasma membrane; apical plasma membrane; membrane; microvillus membrane
Genetic constraint (gnomAD): Loss-of-function variants: 37 observed, 44.6 expected, observed/expected ratio (o/e) 0.83, 90% interval 0.64 to 1.09. The upper end of that interval is the gene's LOEUF score, 1.09, which puts it in group 4 of 6, group 1 being the genes least tolerant of losing a copy. Missense variants: 790 observed, 914.14 expected, observed/expected ratio (o/e) 0.86, 90% interval 0.81 to 0.92. Synonymous variants: 290 observed, 327.95 expected, observed/expected ratio (o/e) 0.88, 90% interval 0.8 to 0.98.
Gene-disease validity (ClinGen):
ClinGen rates the evidence that SLC26A2 causes each of these diseases.
SLC26A2-related skeletal dysplasia (autosomal recessive): Definitive. Any skeletal disorder in which the cause of the disease is a variant in the SLC26A2 gene.
Homologues: Orthologues: chimpanzee SLC26A2 (99% identical), macaque SLC26A2 (96% identical), dog SLC26A2 (87% identical), rabbit SLC26A2 (84% identical), guinea pig SLC26A2 (83% identical), rat Slc26a2 (81% identical), mouse Slc26a2 (81% identical), pig SLC26A2 (76% identical), tropical clawed frog slc26a2 (62% identical), zebrafish slc26a2 (55% identical). Paralogues in human: SLC26A1 (43% identical), SLC26A5 (34% identical), SLC26A4 (32% identical), SLC26A6 (31% identical), SLC26A9 (30% identical), SLC26A3 (30% identical), SLC26A7 (27% identical), SLC26A8 (23% identical), SLC26A11 (20% identical).
Diseases named in the same sentence as SLC26A2 in open-access papers:
SLC26A2 is named in the same sentence as 56 diseases in open-access papers, as found by Europe PMC text mining. Sharing a sentence is not in itself a finding about the gene and the disease. The quoted sentences say what the papers report.
diastrophic dysplasia (30 papers, 2005 to 2025). Diastrophic dwarfism is a rare disorder marked by short stature with short extremities (final adult height is 120cm +/- 10cm), and joint malformations leading to multiple joint contractures (principally involving the shoulders, elbows, interphalangeal joints and hips). "Biallelic LOF variants in SLC26A2, which encodes the predominant sulfate transporter in cartilage and bone, cause a spectrum of osteochondrodysplasias, including diastrophic dysplasia (OMIM 222600)." (PMID 39925707, 2025). "Diastrophic dysplasia (DTD) is a rare autosomal recessive chondrodysplasia caused by biallelic variants in the SLC26A2 gene." (PMID 41162535, 2025). "These cell-based NIPT results showed that the fetus was compound heterozygote for the parental SLC26A2 variants associated with diastrophic dysplasia, in concordance with the invasive test result." (PMID 37829280, 2023). "In the first case (case 2), the parents carried different disease-causing variants in SLC26A2, associated with the development of AR diastrophic dysplasia." (PMID 37829280, 2023). "Diastrophic dysplasia (DTD) is a recessive chondrodysplasia caused by pathogenic variants in the SLC26A2 gene encoding for a cell membrane sulfate/chloride antiporter crucial for sulfate uptake and glycosaminoglycan (GAG) sulfation." (PMID 37454964, 2023). "The allele mutation of SLC26A2 often causes diastrophic dysplasia, so it is also called diastrophic transporter gene." (PMID 35934709, 2022). "Diminished sulfate uptake is caused by mutations in the diastrophic dysplasia sulfate transporter gene (SLC26A2) and causes diastrophic dysplasia, achondrogenesis type IB, atelosteogenesis type II, and a recessive form of multiple epiphyseal dysplasia." (PMID 26213785, 2015). "Diastrophic dysplasia (DTD) is a recessive chondrodysplasia caused by mutations in the SLC26A2 gene encoding for a widely distributed sulfate-chloride antiporter of the cell membrane." (PMID 24927366, 2014). "Cell-based NIPT gave an accurate result in two cases at risk of autosomal recessive disorders, where the parents carried either different diastrophic dysplasia causing variants in the SLC26A2 gene or the same cystic fibrosis disease-causing variant in the CFTR gene." (PMID 37829280, 2023). "Remarkably, numerous human mutations were identified in the STAS domain of different SLC26 transporters causing many diseases including, diastrophic dysplasia (SLC26A2), congenital chloride diarrhea (SLC26A3), Pendred syndrome (SLC26A4), and infertility (SLC26A8/A3)." (PMID 32317970, 2020). "Mutations in SLC26A2 gene result in a spectrum of autosomal recessive chondrodysplasias that range from the mildest recessive form of multiple epiphysial dysplasia (rMED) through the most common diastrophic dysplasia (DTD) to lethal atelosteogenesis type II and achondrogenesis IB." (PMID 34374610, 2021). "Diastrophic dysplasia (DTD), (OMIM #222600) is a rare autosomal recessive chondrodysplasia, caused by pathogenic biallelic variants in the sulfate transporter gene (SLC26A2) gene (OMIM #606718), located on 5q32." (PMID 41162535, 2025). "Variants in the SLC26A2 gene are linked to several chondrodysplasias, including autosomal recessive achondrogenesis type IB (ACG-1B), atelosteogenesis type 2 (AO2), diastrophic dysplasia (DTD), and multiple epiphyseal dysplasia type 4 (EDM-4)." (PMID 41162535, 2025). "Slc26a2 was initially isolated by positional cloning of diastrophic dysplasia and is also called diastrophic dysplasia sulfate transporter (Dtdst)." (PMID 38828713, 2024). "The sulfate transporter gene SLC26A2 is crucial for skeletal formation, as evidenced by its role in diastrophic dysplasia, a type of skeletal dysplasia in humans." (PMID 39508796, 2024). "Another study showed that a specific SLC26A2-STAS mutation associated with the skeletal disease, diastrophic dysplasia, impairs SLC26A2 trafficking to the plasma membrane." (PMID 32317970, 2020).
diastrophic dysplasia (continued). "Sulfate uptake impairment caused by the mutations results in undersulfation of articular and growth plate cartilage of the dtd mouse, an SLC26A2 knock-in model that recapitulates essential aspects of human diastrophic dysplasia." (PMID 24927366, 2014). "A similar correlation has been reported in diastrophic dysplasia (dtd) mice that are mutant for the sulfate transporter gene, Slc26a2." (PMID 23576310, 2013). "Diastrophic dysplasia (DTD, MIM #222600) is a rare autosomal recessive chondrodysplasia caused by biallelic mutations in the sulfate transporter gene (SLC26A2), also known as diastrophic dysplasia sulfate transporter (DTDST) gene." (PMID 34064542, 2021). "Disruption of human SLC26A2 causes a spectrum of osteochondrodysplasias, including achondrogenesis type 1B (OMIM#600972), atelosteogenesis type II (OMIM#256050), recessive multiple epiphyseal dysplasia (OMIM#226900), and diastrophic dysplasia (OMIM#222600)." (PMID 23300579, 2012). "SLC26A2 is an anion transporter responsible for four recessively inherited chondrodysplasias: multiple epiphyseal dysplasia (MED), diastrophic dysplasia (DTD), atelosteogenesis Type II (AO2) and achondrogenesis type IB (ACG1B)." (PMID 15899035, 2005).
chondrodysplasia (15 papers, 2005 to 2025). "We repurposed the FGFR3 inhibitor NVP-BGJ398 to treat SLC26A2-deficient chondrodysplasias, and the treatment only partially ameliorated the phenotype." (PMID 39759111, 2025). "Mutations in SLC26A2 lead to chondrodysplasia, a rare genetic disorder characterized by abnormal cartilage development that affects bone growth." (PMID 39759111, 2025). "Given that, we aimed to investigate the therapeutic effects of melatonin on SLC26A2-deficient chondrodysplasias in the present study." (PMID 39759111, 2025). "In humans, variants in the SLC26A2 gene cause a spectrum of recessively inherited chondrodysplasias." (PMID 39508796, 2024). "SLC26A2 is a sulfate transporter and its mutation causes chondrodysplasia, whilst vasorin is a TGF-β-binding protein that inhibits TGF-β signaling, which is known to have crucial roles in joint homeostasis." (PMID 37388246, 2023). "SLC26A2 linked chondrodysplasias represent a heterogeneous group of skeletal diseases caused by mutations in the SLC26A2 gene encoding for a sulfate transporter present on the cell membrane, also known as diastrophic dysplasia sulfate transporter." (PMID 32295296, 2020). "Of the SLC26 family, dysfunction of SLC26A2, -A3 and -A4 causes chondrodysplasias, congenital chloride diarrhoea or Pendred syndrome." (PMID 17635413, 2007). "In addition to our previous finding of endoplasmic reticulum stress upon SLC26A2 deficiency, we found calcium (Ca2+) overload jointly contributed to SLC26A2-associated chondrodysplasias." (PMID 39759111, 2025). "This is the first study to establish the critical role of SLC26A2-mediated sulfate transport in tooth development, providing insights into the mechanisms behind tooth abnormalities in patients with recessively inherited chondrodysplasias caused by SLC26A2 variants." (PMID 39508796, 2024). "Collectively, these data shed translational insights for drug development and support melatonin as a potential treatment for SLC26A2-related chondrodysplasias." (PMID 39759111, 2025). "Another study in mice found a novel therapeutic target in the lethal forms of SLC26A2-related chondrodysplasias by discovering overactive fibroblast growth factor 3 (Fgfr3) signaling in slc26a2−/− mice." (PMID 34064542, 2021). "This study delved into the mitigating effects of melatonin on defective growth of cartilage and bone caused by SLC26A2 deficiency, with a specific emphasis on its effects on non-lethal chondrodysplasias via postnatal administration." (PMID 39759111, 2025). "Unfortunately, the current challenge lies in the absence of effective pharmaceutical interventions for SLC26A2-associated chondrodysplasias." (PMID 39759111, 2025). "Although SLC26A2-related chondrodysplasia also affects craniofacial and tooth development, its specific role in these processes remains unclear." (PMID 39508796, 2024). "However, although other forms of chondrodysplasias such as progressive pseudorheumatoid chondrodysplasia show symptoms similar to those of RA, no clear link between SLC26A2 and RA can be concluded." (PMID 15899035, 2005).
multiple epiphyseal dysplasia (10 papers, 2005 to 2025). Multiple epiphyseal dysplasias (MED/EDMs) are characterized by epiphyseal anomalies causing joint pain early in life, recurrent osteochondritis and early arthrosis. "In conclusion, our study reported two variants, c.1020_1022del and c.1262 T > C in the SLC26A2 gene associated with multiple epiphyseal dysplasia in a Chinese family." (PMID 38956600, 2024). "This study provides new insight to investigate the mechanism of development of multiple epiphyseal dysplasia, whereby variant of SLC26A2 may contribute to the development of MED-4 by disturbing chondrocyte homeostasis, specifically by inducing disturbance of proliferation and differentiation." (PMID 38956600, 2024). "In Case 6, X-rays at the age of four years confirmed SLC26A2-related recessive multiple epiphyseal dysplasia." (PMID 41595457, 2025). "The homozygous mutation c.835C > T (p.Arg279Trp) is the most common mutation in the SLC26A2 gene, resulting in MED-4 with short stature, multiple epiphyseal dysplasia, scoliosis, double layered patella, brachydactyly and clubfoot." (PMID 29724173, 2018). "In particular, in Case 6, the observed shortening of the long bones by US did not correspond with the phenotype of recessive SLC26A2-related multiple epiphyseal dysplasia (OMIM #226900, ORPHA:93307)." (PMID 41595457, 2025).
colon cancer (5 papers, 2013 to 2024). "In contrast, SLC26A2 is downregulated in colon cancer as the repression of SLC26A2 in colon cancer cells in vitro increases proliferation." (PMID 38684689, 2024). "We proposed that this is due to NF-κB-mediated PRC2 epigenetic silencing of SLC26A2 and ST6GalNAc6 during the very early stages of colon cancer." (PMID 32050430, 2020). "SLC26A2 has been detected to be downregulated in colon cancer biopsies compared with surrounding normal tissue." (PMID 23658834, 2013).
deafness (5 papers, 2015 to 2024). An inherited or acquired condition characterized by the complete loss of the ability to hear from one or both ears. "Among the 300 newly identified candidate deafness genes, slc26a2 were selected for functional studies in zebrafish." (PMID 26375458, 2015). "In particular large clinical deafness pedigrees and sporadic cases must be exploited to identify differences in deaf patients’ DNA by sequencing whole exons of SLC26A2." (PMID 26375458, 2015). "More than 47 mutations have been observed in this gene, but until now, in all the many clinical case reports of SLC26A2-related chondrodyspasia, no deafness or hearing loss has been observed to cosegregate with disease." (PMID 26375458, 2015). "All the results suggest that bioinformatics is capable of predicting new deafness genes and this showed slc26a2 is to be a critical otic gene whose dysfunction may induce hearing impairment." (PMID 26375458, 2015). "More work is needed to determine whether SLC26A2 is a deafness gene." (PMID 26375458, 2015). "Mutations in four human SLC26 genes have been found to be associated with congenital and early-onset Mendelian diseases: chondrodysplasias (SLC26A2), chloride diarrhea (SLC26A3), and deafness with enlargement of the vestibular aqueduct (SLC26A4)." (PMID 26375458, 2015).
osteochondrodysplasia (5 papers, 2012 to 2025). A term referring to disorders characterized by abnormalities in the development of bones and cartilage. "The Miniature Poodle osteochondrodysplasia appears to share even more features with human disorders resulting from loss-of-function mutations in SLC26A2, a member of a distinct family of anion transporter genes." (PMID 23300579, 2012). "The essentiality of sulfate for proper bone and cartilage formation is demonstrated by the spectrum of osteochondrodysplasias in humans with homozygous, loss-of-function mutations in SLC26A2, as well as dog and sheep with homozygous loss-of-function mutations in Slc13a1." (PMID 27412988, 2016). "Interestingly, the osteochondrodysplasia of Miniature Poodles more closely resembles the phenotypes associated with mutation in SLC26A2, a sodium-independent sulfate transporter with ubiquitous expression in human and mouse." (PMID 23300579, 2012).
dysplasia (4 papers, 2015 to 2023). A usually neoplastic transformation of the cell, associated with altered architectural tissue patterns. "The analysis for the parental diastrophic dysplasia SLC26A2 c.-26 + 2T>C and c.1957T>A variants was conducted on nine EVTs." (PMID 37829280, 2023). "In case 2, both parents were unaffected carriers of pathogenic variants in SLC26A2, associated with AR diastrophic dysplasia." (PMID 37829280, 2023). "Indeed, dysregulated cyclin D1 signaling during the G1 phase of the cell-cycle causes reduced chondrocyte proliferation in a mouse model of diastrophic dysplasia due to a p.A386V substitution in the eighth transmembrane domain of solute carrier family 26 member 2 (Slc26a2)." (PMID 25824717, 2015).
multiple epiphyseal dysplasia-4 (4 papers, 2018 to 2025). "Recessive mutations in the SLC26A2 gene cause a phenotype of multiple epiphyseal dysplasia-4 (MED-4)." (PMID 29724173, 2018).
melanoma (3 papers, 2009 to 2020). A malignant, usually aggressive tumor composed of atypical, neoplastic melanocytes. "In the present study, we developed a prognostic and diagnostic biomarker with 5 selected MRGs (A2M, DUSP6, HLA-B, SERPINE2, and SLC26A2), all of which acted as risk factors in melanoma." (PMID 33324561, 2020). "Downregulation of these genes by CtBP1 was confirmed by transient transfection of CtBP1 into the melanoma cell line (Col1A2: 0.31, FAT: 0.52, SLC26A2: 0.72, VCAN: 0.75 compared to mock control set as 1)." (PMID 19216735, 2009).
ulcerative colitis (3 papers, 2013 to 2025). An inflammatory bowel disease involving the mucosal surface of the large intestine and rectum. "However, the studies of SLC26A2 in colon-related diseases are still limited and incompletely understood, especially in ulcerative colitis (UC)." (PMID 40002875, 2025). "The brown module, in which SLC26A2 was located, presented significant correlations with “nFeature_RNA” (number of detected genes in cells), “nCount_RNA” (number of detected mRNAs in cells) and “tissue type” (healthy controls or ulcerative colitis)." (PMID 40002875, 2025). "Decreased levels of SLC26A2 were proved to have a more value in diagnosis of UC patients, and closely correlated with some UC characteristics, including the Mayo score and Paediatric Ulcerative Colitis Activity Index (PUCAI)." (PMID 40002875, 2025). "In addition, SLC26A2 and SLC6A14 mRNA levels have been used as part of a seven gene panel yielding rates of correct prediction, sensitivity, and specificity higher than that with previously available diagnostic indices for ulcerative colitis, Crohn's disease, and irritable bowel syndrome." (PMID 23658834, 2013).
clubfoot (2 papers, 2020 to 2023). The most common congenital deformation of the foot, occurring in 1 of 1,000 live births. "Mutations in genes encoding the ECM proteins COL9A1, COL9A2, COL9A3, COMP and MATN3, as well as the transmembrane glycoprotein involved in matrix organization, SLC26A2, have been associated with clubfoot." (PMID 37964341, 2023). "In a previous study, rMED patients with clubfoot were reported to carry homozygous/compound heterozygous mutations in SLC26A2 at birth." (PMID 32460719, 2020).
inflammatory bowel disease (2 papers, 2023 to 2025). A spectrum of small and large bowel inflammatory diseases of unknown etiology. "However, the studies of SLC26A2 in colon-related diseases are still limited and incompletely understood, especially in inflammatory bowel disease (IBD)." (PMID 40002875, 2025).